HIC1 (HIC ZBTB transcriptional repressor 1)
Diseases named in the same sentence as HIC1 in open-access papers (continued):
Sharing a sentence is not in itself a finding about the gene and the disease.
cancer (87 papers, 2001 to 2025). A tumor composed of atypical neoplastic, often pleomorphic cells that invade other tissues. "In this research, we presented and validated the HIC1 expression landscape in different cancers, and its association with the prognosis of cancer patients was also explored." (PMID 37388742, 2023). "Deep deletion, amplification, and missense mutation were the major types of genetic alteration of HIC1 in pan-cancer." (PMID 37388742, 2023). "HIC1 expression was abnormally expressed in most cancers, and remarkable associations between HIC1 expression and prognostic outcomes of patients in pan-cancer were detected." (PMID 37388742, 2023). "Hypermethylated-in-cancer 1 (HIC1) is a tumor suppressor gene frequently inactivated by epigenetic silencing and loss-of heterozygosity in a broad range of cancers." (PMID 34299935, 2021). "HIC1 (Hypermethylated in cancer 1) is known as a tumor-suppressor gene, which is implicated in many canonical processes of cancer such as cell growth, cell survival, cell migration, and motility." (PMID 35071242, 2021). "HIC1 is a tumor suppressor gene silenced in various human cancers, including CRC, in association with frequent DNA hypermethylation." (PMID 34642302, 2021). "In this study, we explored the specific impact of HIC1 promoter hypermethylation and its association with cancer risk in various solid tumors systematically." (PMID 32398971, 2020). "We sought to perform a more accurate and comprehensive meta-analysis to assess the association between HIC1 promoter methylation and cancer risk." (PMID 32398971, 2020). "The tumor suppressor gene HIC1, which encodes a transcriptional suppressor, is involved in many cancer processes, such as cell survival, growth, and motility." (PMID 31680974, 2019). "One of them is hypermethylated in cancer 1 (HIC1), which encodes a transcriptional repressor with plentiful partners and targets and is involved in many cancer processes, such as cell survival, growth, and motility." (PMID 31680974, 2019). "Hypermethylation leading to the loss of hypermethylated in cancer-1 (HIC1) gene expression occurs in many different types of human cancer." (PMID 27793057, 2016). "Due to promoter hypermethylation, the silence of HIC1 is implicated in many canonical processes of cancer such as cell survival upon genotoxic stress, cell migration and motility." (PMID 27107418, 2016). "These theories could help shape future research to find out how these mutations affect the HIC1 protein's function, which is essential to the growth of many cancer forms." (PMID 38646326, 2024). "These hypotheses may aid in the design of additional studies to determine the impact of these mutations on the function of the hic1 protein, which is critical to the development of numerous cancer types." (PMID 38646326, 2024). "Therefore, HIC1 has the potential to act as a biomarker associated with cancer immunotherapies and predict immunotherapy responses in cancer patients." (PMID 37388742, 2023). "In summary, these results indicated that HIC1 may function as a prognosis-related risk factor in several cancers, including ACC, MESO, KIRP, TGCT, and UVM, and a prognosis-related protective factor in BLCA, CHOL, PCPG, THCA, and UCEC." (PMID 37388742, 2023). "Our results indicated that the expression level of HIC1 is associated with TMB in 20 cancer types and MSI in 5 cancer types, such as STAD, READ, SKCM, and DLBC, suggesting the promising potential of HIC1 as a biomarker for predicting the efficacy of cancer immunotherapy." (PMID 37388742, 2023). "In summary, our results indicate that HIC1 promoter methylation may contribute to cancer risk in several cancer samples, suggestive of the close connection of HIC1 promoter methylation with cancer development." (PMID 32398971, 2020). "Therefore, the associations of HIC1 with cancer prognosis may attribute to its ability to mediate the body’s immune response." (PMID 37388742, 2023).
cancer (continued). "Hence confirming the relationship between HIC1 promoter methylation and cancer risk." (PMID 32398971, 2020). "Because HIC-1 silencing has been shown to be significantly associated with the clinical features of cancer, including survival, pathological stage, and prognosis, these features maybe closely related to cancer drug resistance, invasion, and metastasis." (PMID 30202238, 2018). "Based on the information above, we propose that HIC1 potentially controls the proliferation and invasion of cancer cells by regulating AR expression and subsequently modulating the IRS2/PI3K/AKT pathway." (PMID 41050263, 2025). "These analyses provided a deeper understanding of the potential roles of HIC1 and GSDMD in different cancers and their underlying interactions." (PMID 40279559, 2025). "These complement and integrin dysregulations mirror immune suppression patterns in smoking, with shared epigenetic modifications affecting cancer-related genes like HIC1, though vaping avoids certain methylation changes (e.g., cg05575921) seen in smoking." (PMID 41155303, 2025). "Our results highlighted that HIC1 plays an important role in the progression and therapy of various cancers, thereby offering new insight into cancer immunotherapy." (PMID 37388742, 2023). "To further explore the biological functions and downstream signaling pathways of HIC1 in different cancer types, we conducted KEGG and GO analysis." (PMID 37388742, 2023). "The prognostic value of HIC1 was illustrated by Kaplan-Meier curves and univariate Cox analysis, followed by the genetic alteration analysis of HIC1 in pan-cancer." (PMID 37388742, 2023). "To illustrate the predictive value of HIC1 in cancer immunotherapy treatment, we further investigated the relationship of HIC1 expression with TMB and MSI, two biomarkers that are closely connected with cancer immunotherapy efficacy." (PMID 37388742, 2023). "Our investigation provided an integrative understanding of the clinicopathological significance and functional roles of HIC1 in pan-cancer." (PMID 37388742, 2023). "It was also detected that HIC1 expression was positively related to several immunestimulators in different cancers, such as CXCL12 and TNFRSF4, and was negatively connected with IL-6R in TGCT." (PMID 37388742, 2023). "Currently, the functions of HIC1 genetic alternations in cancer immunological activity are still largely known and warranted further investigation." (PMID 37388742, 2023). "As determined by pan-cancer prognostic analyses, high HIC1 expression was significantly correlated with improved OS, DFS, DSS, and PFS in ACC, OS, DSS, and PFS in UVM, DSS, and PFS in KIRP, OS in MESO, and TGCT." (PMID 37388742, 2023). "Though we have comprehensively conducted numerous analyses to illustrate and validate the roles of HIC1 in pan-cancer, there are still some limitations in our research." (PMID 37388742, 2023). "To explore the prognostic significance of HIC1 in pan-cancer, we first conducted the univariate Cox regression analysis to illustrate the associations of HIC1 with OS, DFS, DSS, and PFS in different cancer types." (PMID 37388742, 2023). "Our results suggested that HIC1 plays an important role in the chemokine signaling pathway in several cancers." (PMID 37388742, 2023). "We also found that HIC1 was significantly correlated with the sensitivity of several anti-cancer drugs, such as axitinib, batracylin, and nelarabine." (PMID 37388742, 2023). "HIC1 was significantly correlated with T cells, macrophages, and mast cell infiltration in different cancers." (PMID 37388742, 2023). "Future studies should focus on the roles of HIC1 in mediating cancer drug resistance through the regulation of ferroptosis." (PMID 37388742, 2023). "In summary, this comprehensive pan-cancer analysis of HIC1 reveals the expression pattern and role of the ferroptosis-related gene HIC1 in different cancer types." (PMID 37388742, 2023).
cancer (continued). "Our findings suggested that HIC1 can function as a potential biomarker for predicting the prognosis, immunotherapy efficacy, and drug sensitivity with immunological activity in cancers." (PMID 37388742, 2023). "The potential of HIC1 in predicting the immunotherapeutic efficacy of anti-PD-1/PD-L1 treatment for cancer patients was further investigated." (PMID 37388742, 2023). "These are hypermethylated in cancer 1 (HIC1), which encodes a transcriptional repressor with multiple partners and targets and is involved in various cancer functions, including cell longevity, proliferation, and migration." (PMID 36793341, 2022). "Concurrent methylation of RassF1A and HIC1 has been reported in advanced ovarian cancer, and HIC1 demonstrates enhanced concordant hypermethylation with other genes in advanced myelodysplasia syndrome, suggesting that disruption of HIC1-associated networks may be critical for cancer initiation." (PMID 35251985, 2022). "HIC1 (hypermethylated in cancer 1), is a member of ZBTB family (ZBTB29) that has been extensively studied in cancer." (PMID 34349770, 2021). "After manual curation for biological functions involved in cancer development, both HIC1 (family SPS.14) and PDLIM2 (family SPS.7) were selected as final candidate genes and further validated by Sanger sequencing." (PMID 33672345, 2021). "HIC1 is a tumor suppressor gene frequently inactivated by promoter hypermethylation in many types of human cancers." (PMID 33227080, 2020). "First, we tried to change HIC1 expression levels to estimate the role of HIC1 in cancer cell growth." (PMID 31680974, 2019). "Increased IL-6 was found in the supernatant of isolated CAFs, which suppressed HIC1 expression in cancer cells and promoted BrCA cell proliferation." (PMID 31795965, 2019). "Although studies have identified HIC-1 as having frequent changes in hypermethylation or loss of heterozygosity in many human cancers, the molecular mechanisms through which HIC-1 inhibits cancer progression remain poorly understood." (PMID 30202238, 2018). "HIC-1 is involved in several complex biological functions in the regulation of drug resistance in cancer, including cell survival, cell growth, cell motility, and cell migration." (PMID 30202238, 2018). "Growing evidence has suggested that the protein expression level of HIC-1 is correlated with prognosis in patients with cancer." (PMID 30202238, 2018). "Previous studies have reported that the expression of HIC-1 is decreased in many human cancers owing to promoter hypermethylation." (PMID 30202238, 2018). "Hypermethylated in cancer 1 (HIC1) is a tumor suppressor gene that is frequently deleted or epigenetically silenced in a variety of human cancers." (PMID 29914167, 2018). "The protein analysis revealed that HIC-1 protein levels were also elevated based on the saRNA transfection for the two cancer cell lines, compared with that of the control cells." (PMID 25435951, 2015). "Hypermethylated in cancer-1 (HIC1) is a transcriptional repressor of the SIRT1 promoter [[A48]] that helps prevent age-dependent cancers in mice." (PMID 24360018, 2013).
cancer (continued). "Several well-known cancer-associated genes (including ADAMTS9, CCND1, HIC1, etc.)exhibited consistently disrupted methylation and expression statuses in the majority of the bladder urothelium cancer samples." (PMID 22140553, 2011). "HIC1 is also a potential tumor suppressor gene; it is frequently hypermethylated and its expression is downregulated in several types of cancer." (PMID 20634891, 2010). "HIC1 is a tumor suppressor gene that aids in the prevention of cancer." (PMID 38646326, 2024). "Numerous studies have been conducted on HIC1 in relation to cancer." (PMID 38646326, 2024). "Furthermore, we explored the relationship between HIC1 expression levels and the abundance of infiltrating immune cells in the specific cancer type." (PMID 37388742, 2023). "Firstly, although we have validated the expression pattern in our clinical samples, the associations of HIC1 with immunotherapeutic efficacy and anti-cancer drug sensitivity have not been validated in our own cohorts." (PMID 37388742, 2023). "Recent work has found that HIC1 can regulate ferroptosis during cancer progression." (PMID 37388742, 2023). "Dynamic monitoring of HIC1 expression may be a valuable approach to effectively evaluate the immunotherapeutic responses of cancer patients, thus helping choose the most suitable therapy strategy for individual cancer patients." (PMID 37388742, 2023). "Furthermore, the most exciting finding was that HIC1 expression was significantly correlated with the response to PD-1/PD-L1 inhibitors in cancer treatment." (PMID 37388742, 2023). "Recent work has suggested the regulatory roles of HIC1 in ferroptosis during cancer progression." (PMID 37388742, 2023). "Moreover, we also explore the relationship between HIC1 expression and the anti-cancer drug sensitivity of cancer patients." (PMID 37388742, 2023). "Our findings showed that HIC1 is closely related to the sensitivity of multiple anti-cancer drugs, especially small molecule inhibitors, including MEK inhibitors trametinib and PD−98059, indicating HIC1 plays a critical role in predicting the sensitivity of anti-cancer drugs." (PMID 37388742, 2023). "Generally, HIC1 plays a critical role in various cancers, however, there is no pan-cancer analysis of HIC1 and the immune-mediating functions of HIC1 in cancers are largely unknown." (PMID 37388742, 2023). "HIC1 was reported to inhibit cancer progression via targeting the Yap pathway in BC." (PMID 35501800, 2022). "Furthermore, the putative novel miRNA EGCG-MDAMB231-5 targets MBP (Myelin Basic Protein), HIC1 (hypermethylated in cancer 1), and P3H2 (Prolyl 3-Hydroxylase 2), SLC6A2 (Solute Carrier Family 6 Member 2) genes." (PMID 36276982, 2022). "Indeed, abnormal DNA methylation of RassF1A and HIC1 is involved in the transformation of MSCs to cancer-like stem cells." (PMID 35251985, 2022). "The variant [g.31856C>T (rs1385460518)] may create a BHLHE22 (basic helix-loop-helix family member E22) binding site, and modify the site for HIC1 (hypermethylated in cancer 1)." (PMID 34193080, 2021). "Methylated HOXA9, SOX1, and HIC1 exhibited the highest sensitivity, specificity, AUC, and accuracy for cancer detection in both singleplex and multiplex MethyLight assay, thereby asserting that their promoter hypermethylation was highly cancer-specific." (PMID 34778370, 2021). "Since then HIC1 methylation has been confirmed in cell lines and tissues in various cancers." (PMID 32398971, 2020). "Even though our data conclusively point to HIC1 promoter methylation associated cancer risk, we acknowledge the absence of some relevant socio-demographic data such as age and gender for further analysis." (PMID 32398971, 2020).
cancer (continued). "However, our analysis is limited by lack of data in this regard hence preventing a deeper probe into the correlation of HIC1 promoter methylation with cancer subtype and stage." (PMID 32398971, 2020). "HIC1 had been previously found to exert important influence on cancer, so there might be a certain regulatory mechanism in the upstream of HIC1." (PMID 31680974, 2019). "Tumor suppressor genes HIC1 and RassF1A are hypermethylated in various cancers." (PMID 30249017, 2018). "Bioinformatics analysis of miR-4532 has shown that hypomethylated in cancer-1 (HIC-1) may be an miRNA target gene involved in the regulation of resistance of cancer cells to chemotherapeutic drugs." (PMID 30202238, 2018). "The region between these two domains has been shown to contain protein-protein interaction motifs/domains including HIC1 (hypermethylated in cancer 1) binding domain (aa 1355–1451) and GR (glucocorticoid receptor) binding domains (aa 1635–2285), which partially overlaps with BAF250_C (aa 1974–2231)." (PMID 30307988, 2018). "Examination of HIC1 and RassF1A methylation or tubulin expression might therefore help predict the best cancer treatment course." (PMID 30249017, 2018). "Additionally, increasing evidence shows that HIC1 is aberrantly hypermethylated in multiple common types of human cancer tissues, including breast, medulloblastomas, gastric, hepatocellular carcinoma, colorectal, cervical and lung tumors." (PMID 27107418, 2016). "In many different human cancers (including prostate, hepatocellular, pancreatic, renal cell carcinoma, breast cancers and esophageal cancers, HIC1 is epigenetically inactivated but not mutated." (PMID 27793057, 2016). "Finally, immunohistochemical analyses of NSCLC tissue microarrays (TMAs) show that expression of nuclear HIC1 in para-carcinoma was 52.2%, while its expression in carcinoma was only 15.4%." (PMID 27107418, 2016). "Moreover, the percentage of methylated HIC1 promoter in 10 primary NSCLC carcinoma tissues was higher than in the respective para-carcinoma tissues." (PMID 27107418, 2016). "This inactivation of HIC1 might impel cancer cells to alter survival and signaling pathways or lineage-specific transcription factors during the early stages of tumorigenesis." (PMID 26510908, 2015). "The upregulation of HIC-1 resulted in obvious anti-cancer effects." (PMID 24489730, 2014). "The inactivation of HIC-1 resulted in upregulated SIRT1 expression in normal or cancer cells." (PMID 24489730, 2014). "For example, N-Myc and c-Myc complete positive feedback loops that promote SIRT1 expression and activity, and the negative regulator of SIRT1 hypermethylated in cancer 1 (HIC1) is commonly epigenetically repressed in cancer, allowing for an increase in SIRT1 activity." (PMID 24258275, 2013). "One possible scenario that ties this role of SIRT1 to a cascade of epigenetic events observed in cancer comes from our recent observation that HIC1, a gene that is frequently epigenetically silenced early in tumorigenesis, can be localized to the SIRT1 promoter." (PMID 16596166, 2006). "HIC1 is hypermethylated and transcriptionally silent in several types of human cancer." (PMID 16248899, 2005).